IL13 (interleukin 13)
Diseases named in the same sentence as IL13 in open-access papers (continued):
Sharing a sentence is not in itself a finding about the gene and the disease.
Allergy (continued). "TH2-type CD4+ T cells and the cytokines that produce IL-4, IL-5, and IL-13 are considered major players in the pathophysiology of allergic diseases." (PMID 36364962, 2022). "Th2 cells can secrete IL-3, IL-4, IL-5, IL-10, and IL-13, and these cells can thereby mediate B-cell differentiation through IL-4, participate in allergic reactions and mediate macrophage deactivation through IL-4, IL-10 and IL-13." (PMID 36225183, 2022). "In contrast, Th2 cells, which produce IL-4, IL-5, IL-6, IL-9, IL-10, and IL-13, induce strong antibody responses by B cells, induce eosinophil activation, and are responsible for allergic reactions." (PMID 35646978, 2022). "As a primary activator of Th2 cells, IL-6 leads to the secretion of IL-4 and IL-13, promoting the Th2 immune response, which is considered pivotal in the pathogenesis of allergy." (PMID 33525403, 2021). "Further, IL-13 is well-known to have direct implications on lung tissue remodeling, airway obstruction, and acute/chronic lung damage in both allergy and chronic obstructive pulmonary disease." (PMID 34027204, 2021). "LN cells from OVA-p(GluNAc)-treated mice had significantly reduced IL-13 production into the supernatant, suggesting that this treatment can also be useful in suppressing Th2-mediated reactions such as allergies." (PMID 34630389, 2021). "In contrast, Th2 cytokines produce the cytokines IL-4, IL-10, and IL-13, which stimulate the production of antibodies directed toward large extracellular parasites, including allergies." (PMID 34945585, 2021). "The type 2 Th (Th2) dominance is a key feature of atopy or allergy as these cells predominantly produce interleukin 4 (IL-4), IL-5, and IL-13, which are involved in the initiation and perpetuation of the allergic phenotype." (PMID 33668787, 2021). "Fish oil supplementation in infants at high risk of atopy increased ω-3 PUFA levels and decreased allergen-specific Th2 responses, including IL-13 and IL-5 production, thus suggesting a potential protection against allergy." (PMID 33668787, 2021). "Pro-inflammatory cytokines (e.g., IL-12, IL-25 and IL-13) play an important role in driving allergic conditions including allergic asthma; IL-33, IL-4 and IL-5 are key factors that drive allergy." (PMID 34638811, 2021). "These function as alarm signals activating ILC2s to produce the Th2 cytokines IL-4, IL-13 and IL-9, with critical roles in type 2 immunity and allergy." (PMID 33803079, 2021). "ILC2s respond quickly to allergic reactions mainly by secreting type 2 cytokines and other peptides, such as IL-4, IL-5, IL-13, IL-9, and amphiregulin (Areg), and by intercellular regulation of the cell-to-cell pathway." (PMID 34177881, 2021). "In allergic reactions periostin is involved in type 2 immunity and can be induced by IL-4 and IL-13 in bronchial cells." (PMID 34512647, 2021). "The aim of work was to obtain an antagonist of natural interleukin-13, which blocks the development of an allergic reaction." (PMID 34945953, 2021). "IL-4 and IL-13 are central to type-2 inflammation; therefore, they represent targetable candidates for the amelioration of allergic disease." (PMID 34072723, 2021). "In contrast, type 2 interleukin (IL)-4/IL-5/IL-13-secreting Th (Th2) cells defend against helminth infections and venom exposure and participate in different types of allergic diseases, including asthma, atopic dermatitis, allergic rhinitis, and food allergy." (PMID 34945585, 2021). "ILC2s synthesize and secrete Th2 cytokines (IL-4, IL-5, IL-9, and IL-13), which promote eosinophils and mast cells to participate in allergic reactions." (PMID 34659628, 2021). "M2 macrophages, induced by T helper 2 (Th2) cytokines such as interleukin (IL)-4 and IL-13, reportedly participate in the pathogenesis of allergic diseases." (PMID 33662037, 2021). "Supporting this notion, trans-differentiation of ciliated cells into goblet cells can be induced by IL-13, a major cytokine involved in allergy and inflammatory response." (PMID 32286221, 2020).
Allergy (continued). "A 2017 study showed that IL-17A was involved in the pathophysiology of allergies by increasing the ability of IL-13 to activate signaling pathways such as intracellular signal transduction and activation of transcription factor 6 (STAT-6)." (PMID 32566265, 2020). "Allergy is characterized by the activation of CD4+ Th2 cells and the production of Th2 associated cytokines, such as IL4, IL5, and IL13, as well as levels of IgE, which activates mast cells." (PMID 33255731, 2020). "Th2 cells mainly participate in IgE-mediated allergies through the release of IL-3, IL-4, IL-5, IL-9, IL-10, and IL-13." (PMID 32566265, 2020). "The secretion of mediators by these immune cells, such as the allergy-related Type 2 cytokines IL-4 and IL-13, but also reactive oxygen species and proteases, contribute to the damage of the epithelium." (PMID 33374733, 2020). "Th2 cells can also be regulated by the transcription factor GATA-3 and secrete IL-4, IL-5, IL-13 and other effector cytokines to regulate allergic reaction." (PMID 33194780, 2020). "Cytokine traps targeting IL-33, TSLP, IL-4 and IL-13 are novel tools that nicely complement the use of monoclonal antibodies for the treatment of allergic diseases." (PMID 32754154, 2020). "IL-4 and IL-13 play an important role in mediating allergic reactions which can promote the induction of IgE syntheses and the development of mast cells." (PMID 33256200, 2020). "Dual targeting of IL-4 and IL-13 with Dupilumab, a monoclonal antibody targeting IL-4Rα, has recently entered the clinic for certain allergic diseases." (PMID 32754154, 2020). "STAT1, STAT3, TLR8, IL13, RFX5 gene polymorphisms have been demonstrated as susceptibility loci for the immune dysregulation in various inflammatory and allergic diseases." (PMID 32886659, 2020). "Th2 cells are the main T cell subsets involved in allergic diseases, which release effector cytokines, such as IL-4, IL-10, and IL-13, that will interact with B cells for the synthesis of allergen-specific IgE." (PMID 33224143, 2020). "Given the fact that IL-13 emerged as a promising target for neurodevelopmental diseases therapy and is already a therapeutic target for allergy treatment, a better understanding of maternal-fetal IL-13 signaling in early brain development is warranted." (PMID 31428082, 2019). "Th2 are closely involved in allergy; their immune response involves the production of IL-4, IL-5, and IL-13, which lead to the recruitment and activation of mast cells, basophils and eosinophils, and goblet cell hyperplasia in airway mucosa." (PMID 31683763, 2019). "In recent years, it has become apparent that the role of IL-13 exceeds that of a classical anti-inflammatory cytokine involved in allergy and parasite infections." (PMID 31428082, 2019). "IL-4 and IL-13 are essential for the allergic reactions, which can promote the production of IgE in the plasma B cells." (PMID 30800677, 2019). "Meanwhile, the late phase of an allergic reaction occurring hours after sensitisation will trigger the release of cytokines such as IL-4, IL-5, IL-9, IL-13, TNF-α and IFN-γ that will recruit inflammatory cells and further bring about mast cell degranulation." (PMID 31829185, 2019). "IL-4 and IL-13 as well as the IL-4 receptor complexes that they bind to play key roles in the pathogenesis of allergic diseases." (PMID 31861989, 2019). "Similar results have been reported by our group in a BLG-sensitized mice model, in which we found that the administration of LGG added to EHCF elicited a significant reduction of allergic reaction, and of IL-4, IL-5, IL-13 and specific IgE production." (PMID 30828329, 2019). "TSLP is widely known to induce Th2 responses by elevating Th2 cytokines such as IL-4, IL-5, and IL-13 in allergic diseases, including AD." (PMID 31817146, 2019). "Whereas, late phase of the allergic reaction is recognized by the release of cytokines such as IL-13, IL-4, IL-9, IL-5, IFN-γ and TNF-α after 2 to 6 h of sensitisation." (PMID 31829185, 2019).
Allergy (continued). "This DCS device is potentially capable of detecting interaction levels between IL-4 and IL-13, and subsequently triggering the release of designed ankyrin repeat protein (DARPin) E2_79 when an allergic reaction is recognised." (PMID 31226821, 2019). "ILC2s are key drivers of allergic disease and upon activation express very high levels of IL-5, IL-6, and IL-13, but also secrete many other cytokines, including IL-4, GM-CSF, IL-9, and IL-10." (PMID 31024538, 2019). "The roles for IL-4, IL-5, IL-13, and GM-CSF in allergic diseases are well established, and it is clear that iBET151 has the potential to suppress these responses in ILC2." (PMID 31024538, 2019). "Two prominent cytokines, IL5 and IL13, which promote allergies and eosinophilia, are under the control of IRE1a-XBP1 pathway in Th2 lymphocytes." (PMID 30355343, 2018). "These complex modes of IL-4 and IL-13 action have great implications in the design of effective allergy therapies." (PMID 29868002, 2018). "More recently, mitochondrial Ca2+/calmodulin-dependent protein kinase II has emerged as key mediator of the molecular response in allergy, regulating eotaxin, IL-4, IL-5, IL-13, and eosinophilic inflammation." (PMID 29890625, 2018). "Substantial progress has been made over the past 28 years in understanding the contribution of 4PS (IRS1 or IRS2) to IL-4- and IL-13-stimulated responses in the context of allergic diseases, however, as noted throughout, there is still much work to be done." (PMID 29868002, 2018). "Noteworthy, exacerbated secretion of IL-5, IL-9, and IL-13 has been reported to be a driver of allergic reactions and chronic inflammatory conditions of the lung and skin." (PMID 29467768, 2018). "DC exposed to the ILC2-produced cytokines IL-4 and IL-13 are more prone to licensing a type 2 Th cell response and support the recruitment of memory T helper cells to the inflamed airways during allergy." (PMID 29467768, 2018). "The various allergy parameters IL-4 and IL-13, DARPin E2_79, the total IgE contained in the serum of the donors and the IgE-DARPin E2_79 complexes were monitored by ELISA (I-IV)." (PMID 29062109, 2017). "Review CCL24 research in allergy, some study invariably involved Th2 cell factors IL-4 or/and IL-13." (PMID 28042950, 2017). "Once the early phase of the allergic reaction has developed into a chronic allergic inflammation, the production of IL-4 and IL-13 occurs in a positive feedback loop, which results in an increase in IgE levels." (PMID 29062109, 2017). "The presented DCS device has been optimized to detect the onset of an allergic response and to sense the presence of IL-4 and IL-13 cytokines during the allergic disease." (PMID 29062109, 2017). "ILC2, mirroring Th2 cells, express GATA3, secrete IL4, IL5, IL9, and IL13 and are involved in protection against helminthes and in allergic reactions." (PMID 29081776, 2017). "Using peripheral blood T-cells, it has been shown that a PI3Kδ selective inhibitor inhibits TCR stimulated IFNγ and IL-17 production from healthy subjects, and IL-5 and IL-13 production from patients with allergy." (PMID 27716212, 2016). "All Th2-related cytokines (IL-4, IL-5, IL-10, and IL-13) were increased by the allergy induction and inhibited by baicalein." (PMID 27561877, 2016). "Suppression of effector T cells by Tregs from children of mothers with allergies was impaired, especially IL-13 production by Type 2 T helper (Th2) cells (P = 0.026)." (PMID 27646403, 2016). "Interleukin-13 (IL-13), a typical Th2 cytokine, is a central mediator of IgE-mediated allergic diseases." (PMID 27187364, 2016). "Prompted by published data that levels of IL-13 are higher in allergic diseases and IL-13 modulates other gene transcription, we exposed B cells from healthy individuals to Th2 cytokines IL-4, or IL-5, or IL-13 in the culture." (PMID 27825134, 2016).
Allergy (continued). "IL-13 plays a central role in the promotion of an allergic inflammatory eosinophilic reaction in allergic diseases via IgE isotype switching." (PMID 27814709, 2016). "We demonstrated that pioglitazone treatment inhibited female Th2 differentiation by reducing both IL-4 and IL-13 production, which are important for allergic disease pathogenesis." (PMID 27548145, 2016). "IL-13 is a Th2 cytokine and is thought to be involved in allergic reactions through its role in promoting the release of IgE antibodies from B cells and favoring Th2 cell differentiation." (PMID 26907333, 2016). "One of the pathological features of allergic diseases is the over-production of T helper (Th) 2 cytokines, including IL-4, IL-5, IL-13, etc., in the sera and the local tissue." (PMID 27825134, 2016). "Th2 cytokines are known to promote the immune response to parasites: IL-4 and IL-13 play a role in the induction of allergy as they stimulate B-cell growth and IgE production, whilst IL-5 typically induces eosinophil differentiation and growth." (PMID 26582546, 2015). "IL-4, IL-13, eotaxin, and CysLT play very important roles in allergy, and their concordant actions in bone-marrow suggest that IL-17A effects on bone-marrow are generally attenuated by mediators of allergy, in a way consistent with in vivo observations." (PMID 26199466, 2015). "Histamine upregulates Th2 cells proliferation and production of Th2 cytokines, such as IL-4, IL-5, IL-10, and IL-13, and thus drives to development of allergies." (PMID 25960757, 2015). "In a study of macrophages in lung inflammation, mir-124 expression was up regulated in macrophages by IL4 and IL13 stimulation as well as by allergy induced inflammation." (PMID 26222688, 2015). "On the contrary cell system, we can detect allergy associated cytokines such as TNF-α, IL-4, IL-13 by RT-PCR in vivo system." (PMID 26317642, 2015). "MGL has been reported to be a marker of alternative activation in murine models of allergy and parasitic infection, with IL-4 and IL-13 being shown to be crucial for its induction and maintenance." (PMID 25951175, 2015). "IL-13 was reported to play an important role in the hypersensitive and allergy responses in the respiratory tract and gut (nematode infestations) and is implicated with fibrosis in scleroderma." (PMID 25343623, 2014). "Settings of high levels of IL-4, IL-13 and IL-17 in AR subjects on multiple allergen exposure support the idea of the heterogeneous nature of allergic disease and the role of Th1/Th2/Th17 balance in the pathogenesis of AR." (PMID 24428928, 2014). "The pathological processes of an allergic reaction are thought to be mediated by Th2-type cells which release interleukins such as IL-5 and IL-13." (PMID 24699261, 2014). "Type I allergic reactions depend on B-cell differentiation and IgE production and histamine release from mast cells induced by IL-4 and IL-13 which helper T cell type II and mast cell produce." (PMID 25276443, 2014). "Interleukin (IL)-13 is a cytokine typically produced during Th2 responses and plays a crucial role in atopy and allergic diseases." (PMID 24848505, 2014). "IL13, a potent mediator of apoptosis in tumor cells, has been demonstrated to be significantly increased in patients with chronic hepatitis infection and allergies." (PMID 23426187, 2013). "In allergy, the immune system is dysregulated with a predominately Th2-biased response characterized by increased levels of IgE and cytokines such as IL-4 and IL-13 while IgG levels and Th1 cytokines such as IFN-γ are reduced." (PMID 24324465, 2013). "Treatment of HConEpiC with IL-13 or IL-4 alone resulted in an increase in the levels of the allergy-related chemokine eotaxin-3 in the conditioned media at all three doses tested for IL-4 and the highest two doses for IL-13 (10 and 100 ng/ml) after 24 h." (PMID 23878502, 2013).
Allergy (continued). "Functional relevance of this observation is demonstrated by increased IL-5 and IL-13 production by CD34+ cells and expression of allergy-associated genes by these progenitor cells after interaction with MC-primed BM-MSCs." (PMID 24381572, 2013). "An additional component of this study was a direct comparison of the cytokines induced by the allergy-related mediators IL-4/IL-13 with TNF-α in two surface ocular cell types, HConEpiC and HConF." (PMID 23878502, 2013). "Th2 T cells: CD4+ T cells that express T-helper 2 (Th2)-type cytokines, such as interleukin (IL)-4, IL-5 and IL-13, and mediate immune responses in allergic diseases and parasitic infections." (PMID 23828644, 2013). "The levels of Th2 cytokines, including IL-4, IL-5, and IL-13, typically increase during an allergic disease." (PMID 23843865, 2013). "IL-4 and IL-13 are closely related cytokines mostly studied for their involvement in allergic diseases (e.g. asthma) and parasitic infections." (PMID 23383283, 2013). "Th2 cells and their cytokines (IL-4, IL-5 and IL-13) are abundant in allergic disease, and these cytokines play a central role in initiating allergic inflammation." (PMID 24330349, 2013). "The use of IL-4Rα −/−, IL-13Rα1 −/−, γc −/− and IL-13Rα2 −/− mice have shown that these receptors are indeed important for controlling functions of IL-4 and IL-13 in allergic diseases and parasitic infections." (PMID 23383283, 2013). "We observed, in SF, a progressive increase in the amount of IL-13, a cytokine usually described in allergic reactions and pulmonary fibrosis." (PMID 22414623, 2012). "Intermittent allergic rhinitis and bronchial asthma belong to the group of allergic diseases mediated by Th2-type cytokines, such as IL-4, IL-5, IL-13." (PMID 22349136, 2012). "This region of the human chromosome 5 also contains many other candidate genes for allergic diseases such as interleukins - IL-3, IL-4, IL-5, IL-9, IL-13; macrophage colony stimulating factor (CSF) and β2-adrenergic receptor (ADRB2)." (PMID 21410962, 2011). "It has been reported that p38 MAPK activation can activate transcription factors that result in the expression of IL-4, IL-5, and IL-13 in human T cells in response to antigen exposure in allergic disease." (PMID 21303540, 2011). "Oct-1 has been previously shown to be important in regulating the expression of IL13 which is a key regulator of Th2-mediated inflammation in allergic diseases." (PMID 21410962, 2011). "Type 2 response is related to secretion of IL-4, IL-5, IL-9 and IL-13 which promote induction of IgE and allergic response." (PMID 20184725, 2010). "In fact, a daily low intake in healthy volunteers of 60 ml AndoSanTM for 12 days gave a significant 50% reduction in levels of the allergy-promoting cytokine IL-4 in blood and left the other allergy-related cytokines IL-5, IL-7 and IL-13 at negligible levels." (PMID 19416507, 2009). "GATA-3 plays a critical role in regulating the expression of the cytokines interleukin (IL)-4, IL-5, and IL-13 from T helper-2 (Th2) cells and therefore is a key mediator of allergic diseases." (PMID 19436703, 2009). "Inflammation in allergic diseases such as asthma, rhinitis, and atopic dermatitis is mediated via expression of the cytokines interleukin (IL)-4, IL-5, and IL-13 from T helper-2 (Th2) cells." (PMID 19436703, 2009). "Allergic diseases are characterized by the presence of Th2 cells and related cytokines, such as interleukin-4 (IL-4), IL-5, IL-9, and IL-13 with the subsequent development of eosinophils infiltration and chronic inflammation." (PMID 16677403, 2006). "Unlike TH1 cytokines that directly affect the stress axis, TH2 cytokines, especially IL-4 and IL-13, are involved in the isotype switching from IgM to IgE, which is the antibody responsible for the generation of classical allergic reactions." (PMID 16759987, 2006).